VDAC1 (voltage dependent anion channel 1)
Diseases named in the same sentence as VDAC1 in open-access papers (continued):
Sharing a sentence is not in itself a finding about the gene and the disease.
breast carcinoma (continued). "Interestingly, our present results in breast cancer were consistent with the reports in pancreatic cancer and colorectal cancer, which indicated VDAC1 expression was upregulated in tumor and promoted the growth and invasion of cancer cells." (PMID 33680287, 2021). "As in GBM, VDAC1 is also over-expressed in patient-derived lung and breast cancer samples." (PMID 30544833, 2018). "Also, we found a significant positive correlation between the gene expression of VDAC1 and histological grade in breast cancer." (PMID 25333947, 2014). "Similarly, expression was low when VDAC1 expression was low and so our signature of genes covariant with VDAC1 in NSCLC data exhibited the same expression patterns in breast cancer data." (PMID 21297950, 2011). "Therefore, whether inhibitors targeting DYNLT1 can be combined with VDAC1 inhibitors to achieve a therapeutic effect in breast cancer remains to be further explored." (PMID 37280526, 2023). "Besides, VDAC1 involved in bromodomain inhibitor resistance in breast cancer." (PMID 37700273, 2023). "Similarly, it has been reported that VDAC1 is highly expressed in breast cancer tissues, which may predict the poor prognosis of breast cancer cases, especially triple-negative breast cancer." (PMID 35958281, 2022). "Therefore, lidocaine may promote apoptosis in breast cancer cells by inhibiting VDAC1 expression from inhibiting breast cancer cell activity." (PMID 36042412, 2022). "We have demonstrated that silencing VDAC1 expression in tumors by 2′-O-Methyl-modified siRNA specific to human (h)VDAC1 (si-hVDAC1-2A) reduced cellular ATP levels and cell proliferation, and inhibited solid tumor development and growth in glioblastoma, cervical, lung and breast cancers." (PMID 34200480, 2021). "Also, we found a significant positive correlation between the gene expression of VDAC1 and histological grade in breast cancer, which suggests that the expression pattern of VDAC1 and its interacting genes may serve as indicators for cancer prognosis." (PMID 25333947, 2014). "MCF-10A cells transfected with pmOGT-HaloTaq showed a significant decrease in VDAC1, VDAC2, and VDAC3 mRNA levels, whereas in MDA-MB-231 and Hs578t breast cancer cells only VDAC3 and VDAC1 mRNA levels decreased significantly after mOGT upregulation." (PMID 38473405, 2024). "In summary, depleting VDAC1 effectively targeted radio- and chemo-resistant CSCs in GBM, breast cancer, and BC, leading to their differentiation into mature, non-replicating cells and, thereby, preventing tumor recurrence." (PMID 39456237, 2024). "In contrast, most of the other potential targets of miR-660-5p, including VDAC1, TPD52L2, and YTHDF1, play oncogenic roles in breast cancer." (PMID 39709500, 2024). "Our previous study demonstrated that reducing VDAC1 expression in GBM and breast cancer led to comprehensive changes in cancer hallmarks." (PMID 39456237, 2024). "Overall, we found two novel FTD-COVID-19 comorbid genes, GFAP and RTN4, and five novel FTD-Breast cancer comorbid genes, AKT3, GFAP, ADCYAP1R1, VDAC1, and C4A, in this study." (PMID 37834358, 2023). "Next, we evaluated the impact of VDAC1 on breast cancer in vitro by transfecting BT549 and McF-7 cells with VDAC1 overexpression plasmid plvx-VDAC1 and control plasmid plvx-Con, respectively." (PMID 36750173, 2023). "For the five FTD-Breast cancer comorbid genes (AKT3, GFAP, C4A, VDAC1, ADCYAP1R1), we analyzed the alterations in the genetic profiles among the different subtypes of Breast cancer." (PMID 37834358, 2023). "Our results showed that the genes AKT3, GFAP, ADCYAP1R1, VDAC1, and C4A have significant transcriptomic alterations in FTD along with the comorbidity status with COVID-19 and breast cancer." (PMID 37834358, 2023).
breast carcinoma (continued). "In the breast cancer cell line MCF7, P4 elicits changes in the expression of S100A11, S100A10, calreticulin, VDAC1, SERCA3, and SERCA1, resulting in a barely Ca2+ efflux from the endoplasmic reticulum as well as impaired membrane potential in the mitochondria." (PMID 33076541, 2020). "Silencing of the mitochondrial protein VDAC1 (Voltage-Dependent Anion Channel 1) inhibits cell growth in GBM, lung cancer and breast cancer." (PMID 33193654, 2020). "Moreover, the effects of VDAC1 depletion on a network of key regulators of cell metabolism, cancer stem cells, TFs, and other factors, finally leading to differentiation, are coordinated and are common to GBM and lung and breast cancer cell lines, despite differing in origin and carried mutations." (PMID 31195298, 2019). "We showed that depleting VDAC1, which is overexpressed in many tumors, including GBM and lung and breast cancers, resulted in a decreased expression of glycolysis-, Kreb’s cycle-, and OXPHOS-related enzymes, reflecting reduced anaplerotic and OXPHOS reactions." (PMID 31195298, 2019). "We showed here that reprogramming metabolism via silencing VDAC1 expression affects the expression of key transcription factors in GBM, lung and breast cancers." (PMID 30544833, 2018). "Here, we demonstrated that VDAC1 silencing highly reduced the expression of CSC markers in GBM and lung and breast cancer, as revealed using IHC, immunoblotting or q-RT-PCR." (PMID 30544833, 2018). "Here, we present the novel concept for modulating the metabolism of cancer cell by depleting VDAC1, a protein that has a central role in cell energy and metabolism and which is over-expressed in many tumours, including GBM, lung and breast cancers." (PMID 30544833, 2018). "Additionally, in a TNBC subset of breast cancers of all subtypes, low CYCS and high VDAC1 (voltage-dependent anion channel-1) protein levels were linked significantly to reduced 5-year DFS." (PMID 40806359, 2025). "SB5 suppressed both MMP9 and spheroid formation in prostate cancer (RV1) cell line and breast cancer (MCF‐7) cell line differently than SB4 but both compounds did not affect the VDAC1 protein expression." (PMID 41179704, 2025). "DYNLT1 is a new therapeutic target for breast cancer, and the regulatory mechanism between DYNLT1 and VDAC1 in breast cancer has not been reported." (PMID 37280526, 2023). "Results showed that the gene VDAC1 is highly expressed in all the subtypes, whereas AKT3 is expressed in TNA, TNB, and H-subtypes, indicating that these genes have a significant role in Breast cancer at the single-cell level." (PMID 37834358, 2023). "Moreover, spatial transcriptome data from clinical breast cancer samples also revealed extensive spatial colocalization of DLYNT1 and VDAC1 in cancer epithelial cells." (PMID 37280526, 2023). "In contrast, higher VDAC1 protein level was found in breast cancer tissues compared with non-cancer tissues and was correlated with poorer overall survival in TNBC patients." (PMID 36186902, 2022). "Thus, VDAC1, regulating a continuum of cellular functions from metabolism to cell differentiation, offers a target for treating GBM, lung and breast cancer via attack on the interplay between metabolism and oncogenic signaling networks." (PMID 30544833, 2018). "Simultaneously, we examined the expression of VDAC1 in human breast cancer cells and human mammary epithelial cells, and the findings revealed that, compared with normal mammary epithelial cells HMEC, the expression of VDAC1 was higher in human breast cancer cells BT549 and MCF-7." (PMID 36750173, 2023).
breast carcinoma (continued). "Also, the VDAC inhibitor, JQ1, prevents the activity of bromodomain-containing proteins (BRD), including BRD4, that is enriched in patients with basal luminal breast cancer, suggesting that VDAC1 is relevant in cancer cell progression and is a hallmark of poor prognosis." (PMID 33511135, 2020). "Moreover, VDAC1 deletion resulted in similar reprograming of cell metabolism in the three types of cancer cell lines addressed here (GBM and lung and breast cancers), regardless of cellular origin or mutations carried." (PMID 31195298, 2019). "Despite the decrease in VDAC1 and VDAC2 mRNA, we observed that mOGT did not affect the levels of VDAC1 and VDAC2 proteins in the mitochondria of normal and breast cancer cells." (PMID 38473405, 2024).
lung carcinoma (39 papers, 2012 to 2025). "Secondly, we found that the gene signature, VAG, which is associated with apoptosis and composed of VDAC1 and its interacting genes, is capable of predicting recurrence-free survival in breast, colon, and lung cancers." (PMID 25333947, 2014). "Furthermore, we observed that the expression of EPOR is associated with the expression of the mitochondrial marker VDAC1 in tissue arrays of lung cancer patients, suggesting that EPOR indeed helps to regulate mitochondrial biogenesis in tumors of cancer patients." (PMID 36052260, 2022). "In a 2022 study on lung cancer stem-like cells, siRNA-mediated VDAC1 knockdown resulted in metabolic reprogramming, characterized by a shift from OXPHOS to glycolysis, ultimately impairing tumor progression." (PMID 40608151, 2025). "Mcl-1 overexpression in lung cancer promotes cell migration by interacting with VDAC1 to enhance mitochondrial Ca2+ uptake and ROS generation." (PMID 40661148, 2025). "It has been demonstrated that in cultured cells and lung cancer patients, hypoxia induces VDAC1 truncation at the C terminus (VDAC1‐ΔC), which is prevented upon silencing HIF‐1α expression." (PMID 39921338, 2025). "Given the high energy demands of CSCs, VDAC1 is often overexpressed in various cancers, including glioblastoma, cervical, and lung cancers, where it facilitates tumor progression and therapy resistance." (PMID 40608151, 2025). "The results suggest that VDAC1 depletion and its peptide can be a possible therapeutic strategy in the treatment of lung cancer." (PMID 39272828, 2024). "Silencing VDAC1 expression was also effective in a chemically induced lung cancer model using the carcinogen urethane, which mimics the clinical scenario of lung cancer." (PMID 39456237, 2024). "We further studied the impact of silencing VDAC1 on the TME using human-derived A549 lung cancer xenografts in mice." (PMID 39456237, 2024). "The results clearly show that lung cancer tissues express high VDAC1 levels compared to those in healthy lung tissues." (PMID 39272828, 2024). "We show that silencing VDAC1 expression in a urethane-induced lung cancer mouse model reprogrammed metabolism, inhibited tumor growth, modulated the tumor microenvironment, and eliminated cancer stem cells (CSCs)." (PMID 39272828, 2024). "The expression levels of VDAC1 in the lung cancer tissue array comprised 10 samples from healthy human donors and 31 from lung cancer patients that were analyzed by IHC using anti-VDAC1 antibodies." (PMID 39272828, 2024). "In our studies using various lung cancer cell lines, we found that siRNA targeting human VDAC1 with specific si-hVDAC1 led to decreased cellular ATP levels and inhibited cell proliferation." (PMID 39456237, 2024). "Here, we focused on metabolic reprogramming and changes in tumor hallmarks in lung cancer by silencing the expression of the mitochondrial gatekeeper VDAC1." (PMID 39272828, 2024). "si-m/hVDAC1-B markedly decreased VDAC1 expression levels in the A549 and H446 cell lines by 90–95% (50 nM or 75 nM), and in the mouse lung cancer 2LL cell line by 60% (50 nM or 75 nM)." (PMID 39272828, 2024). "In our study, we explored the impact of disrupting the production of mitochondrial gatekeeper protein VDAC1 on lung cancer." (PMID 39272828, 2024). "Representative images from healthy and lung cancer tissues were sub-grouped according to staining intensity, with 15% of the cases showing low, 40% medium, and 45% high VDAC1 expression levels." (PMID 39272828, 2024). "In this study, we focused on the effects of metabolic reprogramming via silencing VDAC1 expression in a carcinogenic urethane-induced lung cancer model." (PMID 39272828, 2024). "VDAC1(voltage-dependent anion channel 1), a main factor in the outer mitochondrial membrane, was upregulated in multiple cancers, including lung cancer, breast tumor, cervical tumor, and liver cancer." (PMID 37700273, 2023).
lung carcinoma (continued). "For lung cancer, previous studies have reported the correlation between VDAC1 expression and the initiation and progression of nonsmall cell lung cancer." (PMID 35958281, 2022). "We then validated these findings by analyzing EPOR and VDAC1 expression in arrays of non-small lung cancer tissue from 214 human patients." (PMID 36052260, 2022). "In order to explore the effect of VDAC1 on the metabolic ability of lung cancer cells, we measured the extracellular acidification rate (ECAR) to quantify the glycolysis ability in A549 cells knocking down VDAC1 in A549 cell line." (PMID 34539973, 2021). "The results showed that when the expression of VDAC1 in lung cancer cells was downregulated, both the basic glycolysis level and the maximum glycolysis level decreased significantly." (PMID 34539973, 2021). "VDAC1 is the most abundant and best studied isoform and is highly expressed in different tumors, including lung cancer, pointing to its significance in high energy-demanding cancer cells." (PMID 34200480, 2021). "We previously reported that siRNA specific for human VDAC1 (si-VDAC1) inhibited solid tumor development and growth in cervical and lung cancers and triple negative breast cancer, as well as in GBM." (PMID 32331482, 2020). "Mechanistically, VDAC1 directly interacts with Mcl-1 to regulate the generation of ROS in lung cancer." (PMID 32210729, 2020). "In cultured cells and in lung cancer patients, hypoxia induces VDAC1truncation at the C-terminus (VDAC1-ΔC)." (PMID 29560113, 2018). "We demonstrated that silencing VDAC1 expression using human-specific siRNA (si-hVDAC1) inhibited cancer cell growth, both in vitro and in mouse xenograft models of human glioblastoma (U-87MG), lung cancer (A549), and triple negative breast cancer (MDA-MB-231)." (PMID 30544833, 2018). "VDAC1 expression is related to poor prognosis in breast, colon, and lung cancers, where it has been demonstrated that VDAC1 promotes cell growth by influencing energy metabolism and inhibiting apoptosis." (PMID 30298016, 2018). "VDAC1 overexpression was demonstrated in lung cancer, where C-terminally truncated VDAC1 (VDAC1-ΔC) was present in tumor cells exposed to hypoxia in 50% of 46 patients with lung cancer." (PMID 28824871, 2017). "Additionally, a peptide derived from VDAC1 disrupting this interaction effectively inhibit lung cancer migration." (PMID 40661148, 2025). "Thus, silencing VDAC1 targeting both NSCLC and SCLC points to si-VDAC1 as a possible therapeutic tool to treat these lung cancer types." (PMID 39272828, 2024). "Moreover, both VDAC1 transcript and protein levels were elevated in the lung cancer cell line H358 relative to A549 cells." (PMID 39456237, 2024). "The results point to si-VDAC1 as a potential treatment for lung cancer." (PMID 39272828, 2024). "In this study, we utilized a chemically-induced lung cancer using the carcinogen urethane that produces tumors that are similar to human clinical situation of lung cancer in terms of histology and molecular characteristics, along with si-m/hVDAC1-B, which recognizes both mouse and human VDAC1." (PMID 39272828, 2024). "The silencing of VDAC1 expression in human lung cancer A549 and H446 cell lines and in the mouse lung cancer 2LL cell line was conducted using a modified siRNA, si-m/hVDAC1-B, that recognizes both human and mouse VDAC1." (PMID 39272828, 2024). "Additionally, intravenous treatment of urethane-induced lung cancer mice with the VDAC1-based peptide, Retro-Tf-D-LP4, showed inhibition of tumor growth, and decreased expression levels of metabolism- and cancer stem cells-related proteins." (PMID 39272828, 2024). "Furthermore, in a mouse model of lung cancer, intraperitoneal injection of si-VDAC1 not only inhibited tumor growth but also resulted in tumor disappearance." (PMID 38989148, 2024). "It is concluded that VDAC1 may become a novel marker for early diagnosis and prognosis evaluation of lung cancer." (PMID 36750173, 2023).